TERC (telomerase RNA component)
Synonyms: TR; hTR; TRC3; SCARNA19; TER; DKCA1; PFBMFT2
Gene: Long non-coding RNA gene on chromosome 3 (169,764,610 to 169,765,060, reverse strand). Ensembl gene ENSG00000270141.
Gene Ontology:
Molecular function: telomerase activity
Biological process: telomere maintenance via telomerase
Cellular component: telomerase catalytic core complex
Gene-disease validity (ClinGen):
ClinGen rates the evidence that TERC causes each of these diseases.
dyskeratosis congenita, autosomal dominant 1 (autosomal dominant): Definitive.
Diseases named in the same sentence as TERC in open-access papers:
TERC is named in the same sentence as 142 diseases in open-access papers, as found by Europe PMC text mining. Sharing a sentence is not in itself a finding about the gene and the disease. The quoted sentences say what the papers report.
dyskeratosis congenita (30 papers, 2007 to 2026). Dyskeratosis congenita (DC) is a rare ectodermal dysplasia that often presents with the classic triad of nail dysplasia, skin pigmentary changes, and oral leukoplakia associated with a high risk of bone marrow failure (BMF) and cancer. "Mutations in the TERC gene are believed to be an important cause of the occurrence of the autosomal dominant form of dyskeratosis congenita." (PMID 38940945, 2024). "Previous research found that TERC is associated with hypermethylation in breast cancer and differential methylation in dyskeratosis congenita." (PMID 35571069, 2022). "To address this issue, we established an in vitro cellular model of dyskeratosis congenita, in which we depleted a known causative gene, TERC in human iPSCs." (PMID 30210531, 2018). "Studies in human have also shown that rare mutations in TERC are associated with telomere shortening in individuals with dyskeratosis congenita." (PMID 20885959, 2010). "Mutations in TERC result in a reduction of telomerase activity leading to premature telomere shortening and have been linked to the autosomal dominant form of dyskeratosis congenita and aplastic anemia." (PMID 20885959, 2010). "Furthermore, the RNA‐binding protein ELAVL1 is suggested to enhance telomerase assembly and activity by maintaining TERC RNA cytosine methylation, a process disrupted by genetic mutations within TERC closely associated with dyskeratosis congenita." (PMID 41456942, 2026). "Other conditions linked to telomere dysfunction are also associated to HSC failure and leukemia predisposition such as dyskeratosis congenita (caused by TERC mutation) and a hereditable heterozygous mutation of TERT responsible for autosomal dominant aplastic anemia." (PMID 34736527, 2021). "Genetic anticipation, associated with inter-generational telomere shortening, is seen in various forms of dyskeratosis congenita (DC), for example in families with autosomal dominant DC caused by mutations in the telomerase RNA component (TERC), and other short telomere disorders." (PMID 33142697, 2020). "However, studies have shown that reprogrammed iPSCs isolated from those with TERC-mutated dyskeratosis congenita can restore telomere maintenance due to up-regulated levels of telomerase found in the pluripotent state." (PMID 30210531, 2018). "Mutations in the telomerase RNA component (TERC), an RNA component of telomerase and the template for telomere replication by telomerase, can cause dyskeratosis congenita (DC) and might also be associated with some cases of aplastic anaemia (AA)." (PMID 29138457, 2017). "The CR4/CR5 domain of TERC is known to play this role, since a mutation of this domain found in dyskeratosis congenita (DC) patients decreases its affinity for RNA Pol II, impairing its myelopoietic activity as a result." (PMID 37737237, 2023). "Dyskeratosis congenita (DC)-related TERC U100A mutation impair the association of HuR with TERC, thereby reducing C106 methylation." (PMID 29880812, 2018). "Most human progeroid syndromes result from monogenic defects in nuclear components (e.g. LMNA in Hutchinson-Gilford progeria syndrome, TERC in dyskeratosis congenita), and telomere length has long been observed as a marker of aging." (PMID 34467851, 2021). "TERC (telomerase RNA component), encoding an essential RNA component of telomeres, plays a role in cell proliferative potential, telomerase activity and telomere length, and TERC mutations have been found in autosomal dominant dyskeratosis congenita (DC), aplastic anemia, MDS, and cervical cancer." (PMID 32905346, 2020). "Telomerase dysfunction caused by human TERC mutations is linked to numerous human diseases, including pulmonary fibrosis, human cancer, and premature aging syndromes, such as dyskeratosis congenita (DC) and aplastic anemia." (PMID 29880812, 2018).
dyskeratosis congenita (continued). "Heterozygosity of TERC- and most TERT-mutations can lead to haploinsufficiency and to the clinical phenotype of dyskeratosis congenita, although some TERT mutations cause recessive DKC with heterozygous carriers showing normal blood counts." (PMID 26546739, 2015). "DKC1, mutated in X-linked dyskeratosis congenita, is associated with small nucleolar RNAs, but also with human telomerase RNA (TERC), and it has been suggested that the disease phenotype in dyskeratosis congenita results from a defect in telomere maintenance." (PMID 23785305, 2013). "Genetic linkage analysis of the constitutional marrow failure syndrome dyskeratosis congenita led to the discovery of mutations in the genes DKC1 (which encodes dyskerin) and telomerase RNA component (TERC)." (PMID 19936245, 2009). "Haploinsufficiency for TERC causes the autosomal dominant variant of dyskeratosis congenita (DC)." (PMID 17875000, 2007). "Dyskeratosis congenita (DKC) is a progressive dermatological condition characterized by premature graying and wrinkling, nail dystrophy, and abnormal pigmentation, and caused by mutations in the telomerase RNA component (TERC) and telomerase reverse transcriptase (TERT) genes." (PMID 32518230, 2020). "Dyskeratosis congenita, a rare hereditary disorder complicated by the development of pulmonary fibrosis in 20% of patients, is associated with mutations within either TERT or TERC that lead to decreased telomerase activity." (PMID 23075428, 2012). "TA is also required for the maintenance of normal stem cells, and in patients with dyskeratosis congenita (DKC) inactivating mutations in TERT and TERC may lead to the loss of normal hematopoietic stem cells and aplastic anemia." (PMID 20824134, 2010). "Individuals with dyskeratosis congenita (DC), a cancer susceptibility and inherited bone marrow failure syndrome (IBMFS), have mutations in genes important in telomere biology, including DKC1, TERC, TERT, TINF2, NHP2 and NOP10." (PMID 21113082, 2010). "The human condition dyskeratosis congenita (DC) is associated with heterozygous mutations in TERT and TERC and hemizygous mutations in the telomerase enzyme component dyskerin (DKC)." (PMID 35409012, 2022). "We reported mutations in TERC and telomerase reverse transcriptase (TERT) to be risk factors for apparently acquired aplastic anemia, a marrow failure disease occurring in patients who lack the typical physical anomalies and family history of dyskeratosis congenita." (PMID 19936245, 2009). "Telomeropathies include dyskeratosis congenita (DKC), in which a disease-causing variant is often found within the dyskerin (DKC1) gene on the X chromosome or other telomere maintenance genes such as TINF2, TERC, TERT, CTC1, and other genes." (PMID 40440483, 2025). "Dyskerin mutations are associated in autosomal dominant fashion with another hereditary BMF syndrome, dyskeratosis congenita (DC), but mutations of other members of the telomerase complex, chiefly TERT and TERC, have been implicated in predisposition to both AA and MDS." (PMID 29416752, 2018). "Dyskeratosis congenita (DC) is a disorder of excessive telomere attrition due to defects in the telomerase complex, either related to the disease gene (DKC1), and/or other genes involved in telomere repair (TIN2, TERC, TERT, amongst others)." (PMID 38612901, 2024). "Haploinsufficiency for TERC or TERT leads to progressive telomere shortening and autosomal dominant dyskeratosis congenita (DC)." (PMID 17875000, 2007).
pulmonary fibrosis (23 papers, 2009 to 2026). Chronic progressive interstitial lung disorder characterized by the replacement of the lung tissue by connective tissue, leading to progressive dyspnea, respiratory failure, or right heart failure. "For instance, TERC genetic variants (C108T, 110_113del, 378_451del) have been reported to be significantly linked to pulmonary fibrosis susceptibility." (PMID 41456942, 2026). "This has been observed in families with pulmonary fibrosis carrying monoallelic variants of TERC, TERT, or other genes, resulting in early-onset pulmonary fibrosis and other disorders, such as bone marrow failure." (PMID 40095034, 2025). "Compared with other telomere-related gene variants, pulmonary fibrosis associated with TERC variants typically presents earlier, with a mean onset of about 51 ± 11 years." (PMID 41465275, 2025). "The TERC C/T allele association with TL showed an increased risk of colorectal cancer (longer TL), idiopathic pulmonary fibrosis (shorter TL) and multiple sclerosis (longer TL)." (PMID 38192544, 2024). "The average age of death in ILD smokers with TERT or TERC mutations is 10 years earlier than in mutation-carrying non-smokers, and an association between smoking history and pulmonary fibrosis in TERT mutation carriers ≥40 years of age has been shown." (PMID 33808277, 2021). "Different studies in human and mouse models have attempted to provide biological insights into the association of TERT and TERC polymorphisms with pulmonary fibrosis." (PMID 24391588, 2013). "Our current findings parallel the recently reported association of loss-of-function TERT and TERC mutations with familial idiopathic pulmonary fibrosis." (PMID 19936245, 2009). "Notably, pulmonary fibrosis (PF)‐associated mutations (C108T, 110_113del, and 378_451del) substantially diminished TERC m6A methylation." (PMID 41456942, 2026). "In addition, we also demonstrated that telomerase deficiency due to either TERC or telomerase catalytic subunit TERT knockout induces pulmonary fibrosis with AEC2 senescence and senescence-associated low-grade inflammation (SALI)." (PMID 34831112, 2021). "Rare telomere-maintenance gene pathogenic variants, such as TERT, TERC, RTEL1, and PARN, are principal causes of pulmonary fibrosis and familial pulmonary fibrosis and are associated with shorter telomeres, earlier disease onset, and poor outcomes." (PMID 41465275, 2025). "The involvement of telomeres in pulmonary fibrosis is also supported by evidence that variations in the genes telomere reverse transcriptase (TERT) and telomerase RNA component (TERC) are associated with development or prognosis of pulmonary fibrosis." (PMID 40903050, 2025). "Previously, a monoallelic missense variant in ZCCHC8 (p.Pro186Leu) was documented to co-segregate with low levels of mature TERC in a single family, where individuals exhibited short telomeres, pulmonary fibrosis, or bone marrow failure." (PMID 39198715, 2024). "A similar study screened 73 probands from the Vanderbilt Familial Pulmonary Fibrosis Registry and found that six (8%) had heterozygous mutations in TERT or TERC." (PMID 34859008, 2021). "The abnormalities identified in lung tissues in the TERC knockout model include poor alveolar integrity, compromised regenerative ability under partial pneumonectomy, and pulmonary fibrosis induced by telomere dysfunction and shortening." (PMID 34831112, 2021). "There are many candidate genes implicated in pulmonary fibrosis, such as IGF-I, IGFBPs, ELMOD2, TERT, TERC, SFTPC, SFTPA2), and MUC5B." (PMID 26447616, 2015). "Indeed, heterozygous variants have been detected in familial forms of pulmonary fibrosis involving TERT (∼15%), RTEL1 (5–10%), PARN (∼5%), and TERC (∼3%)." (PMID 36833253, 2023). "Additionally, we identified four unrelated families in which loss-of-function TERC or TERT gene mutations tracked with marrow failure, pulmonary fibrosis, and a spectrum of liver disorders." (PMID 19936245, 2009).
pulmonary fibrosis (continued). "It is worth mentioning that IPF cases are usually seen in old age, and some relatives of IPF patients with both TERT or TERC mutations and telomere shortening do not develop pulmonary fibrosis, suggesting that aging and environmental factors are also involved in disease pathogenesis." (PMID 34859008, 2021). "Five subjects in this group carried mutations in TERT, two subjects had mutations in TERC, and one fulfilled clinical telomere syndrome criteria, a positive history of thrombocytopenia, a family history of pulmonary fibrosis, but no detectable mutation in TERT, TERC or DKC1." (PMID 31426295, 2019). "Supporting the notion that TERT and TERC deficiency might contribute to pulmonary fibrosis by mechanisms dependent on telomerase activity but not necessarily telomere length, telomerase activity is induced in IPF and NSIP fibroblasts and systemic sclerosis lung compared to healthy donor samples." (PMID 24391588, 2013). "In addition, we found that G2 TERC KO mice display aggravated bleomycin (BLM)-induced pulmonary fibrosis, suggesting that telomere shortening promotes the genesis of pulmonary fibrosis." (PMID 34859008, 2021). "In addition, in IPF, 25% of individuals who have either familial or sporadic pulmonary fibrosis, without h-TERT or h-TERC mutation, have shorter telomeres in their circulating leukocytes." (PMID 24067943, 2013).
lung carcinoma (12 papers, 2015 to 2025). "Increased TERC dosage is associated with elevated expression and enhanced telomerase activity in lung cancer." (PMID 41303594, 2025). "Subjects with at least one C allele of TP53BP1 rs560191 had a significant 2-fold increased risk of lung cancer compared with those with at least one C allele of TERC rs1881984 and the GG genotype of TP53BP1 rs560191." (PMID 33906323, 2021). "But few studies were reported on the association between SNPs in TERC gene and the risk of lung cancer." (PMID 29299136, 2017). "The study was aimed to explore whether the TERT and TERC polymorphisms are associated with the lung cancer risk." (PMID 29299136, 2017). "In the context of lung cancer, genetic variants at several loci have been associated with both LTL and lung cancer risk, including variants near the TERT, TERC, OBFC1, and RTEL1 genes, fundamental to telomere length maintenance." (PMID 37079368, 2023). "We examined for the first time the association between TERC rs1881984 and OBFC1 rs11191865 in relation to lung cancer risk." (PMID 33906323, 2021). "Inspection at the single SNP level indicated that the lung cancer associations were driven mainly through rs7705526 at the TERT gene locus and rs2293607 at the TERC gene locus." (PMID 33941849, 2021). "In this study, genotypes of telomere-related polymorphisms (TERT rs2736100, TERC rs1881984 and OBFC1 rs11191865) were determined in 462 lung cancer cases and 379 controls." (PMID 33906323, 2021). "Five TERC and TERT polymorphisms were genotyped from 554 lung cancer patients and 603 healthy controls." (PMID 29299136, 2017). "Our study indicated that rs10936599 (TERC) and rs10069690, rs2242652 and rs2853677 in TERT and haplotype “TA” of TERT were revealed as risk factors of lung cancer in a Chinese Han population." (PMID 29299136, 2017). "In the case-control study, we investigated the association between SNPs in TERC, TERT genes and the risk of lung cancer in Chinese Han population." (PMID 29299136, 2017). "In conclusion, the study demonstrated that rs10936599 (TERC), rs10069690, rs2242652 and rs2853677 in TERT, and haplotype “TA” of TERT are associated with increased risk of lung cancer in Chinese Han population." (PMID 29299136, 2017). "The results showed that rs10936599 in TERC and rs10069690, rs2242652 and rs2853677 in TERT were revealed as risk factors of lung cancer." (PMID 29299136, 2017). "We found that the allele “C” of rs10936599 (TERC) and the allele “T” of rs10069690 (TERT) were associated with increased risk of lung cancer (OR = 1.32, 95% CI: 1.12-1.55, P = 0.001; OR = 1.41, 95% CI: 1.14-1.76, P = 0.002, respectively)." (PMID 29299136, 2017). "In contrast, blood cell traits and hematological diseases were implicated with a wider range of loci, including TERC, TERT, SENP7, ATM, BBOF1, and MROH8; this result is similar to those for the respiratory function and lung cancers that also involved multiple TL loci." (PMID 32109421, 2020). "In the allele model, the allele “C” of rs10936599 (TERC) and the allele “T” of rs10069690 (TERT) were found to be associated with increased the risk of lung cancer (OR = 1.32, 95% CI: 1.12-1.55, P = 0.001; OR = 1.41, 95% CI: 1.14-1.76, P = 0.002, respectively)." (PMID 29299136, 2017). "On the other hand, TERT and TERC are frequently over-expressed in lung carcinomas, and there is evidence that TERC over-expression may be due to an amplification of 3q26, where TERC gene is mapped." (PMID 26301749, 2015).
lung carcinoma (continued). "In the present study, we found that, in lung carcinomas, the well-established association between dyskerin expression and TERC levels was observed only for those cases where TERC gene was not amplified." (PMID 26301749, 2015). "To clarify this point, we analyzed the connection between dyskerin expression, TERC levels and clinical outcome in two series of primary lung cancers, differing for the presence of TERC gene amplification, a genetic alteration inducing strong TERC overexpression." (PMID 26301749, 2015). "TERT rs2736100 has been relatively frequently examined in lung cancer studies, while TERC rs1881984 and OBFC1 rs11191865 have not yet been examined." (PMID 33906323, 2021). "In conclusion, none of the three polymorphisms (TERT rs2736100, TERC rs1881984 and OBFC1 rs11191865) were associated with lung cancer risk." (PMID 33906323, 2021). "In accord, the association between dyskerin expression and survival was found only in those lung cancer cases not bearing TERC gene amplification." (PMID 26301749, 2015). "We analyzed a total of 60 lung cancers, 30 bearing an amplification of TERC gene and 30 bearing not, first of all by investigating how TERC locus amplification reflects on TERC expression levels." (PMID 26301749, 2015). "Indeed, in lung cancer, the effect of dyskerin expression on prognosis can be ascribed mainly to its activity on TERC stabilization, since no significant repercussion on survival was observed in those tumors where no dyskerin/TERC relationship was found." (PMID 26301749, 2015). "In addition, because of the known role of dyskerin on TERC stabilization, we wondered how TERC levels might be influenced by a conjunct effect of TERC locus amplification and DKC1 expression in lung cancers." (PMID 26301749, 2015). "In the present study, we analyzed the connection between dyskerin expression, TERC expression and clinical outcome in two series of primary lung cancers, differing for the presence or absence of TERC gene amplification, a genetic alteration inducing strong TERC overexpression." (PMID 26301749, 2015).